CHGA (chromogranin A)
Diseases named in the same sentence as CHGA in open-access papers (continued):
Sharing a sentence is not in itself a finding about the gene and the disease.
adenocarcinoma (38 papers, 2004 to 2025). A common cancer characterized by the presence of malignant glandular cells. "Macroscopically, adenocarcinoma cells were present on both sides of the NET, while microscopically, some adenocarcinoma cells were positive for neuroendocrine markers (synaptophysin and chromogranin A)." (PMID 40511448, 2025). "Pathological examination revealed poorly differentiated adenocarcinoma with neuroendocrine features of positive synaptophysin and chromogranin-A expressions." (PMID 30458812, 2018). "In a study from our group, we found blood chromogranin A elevation in six adenocarcinomas." (PMID 34948181, 2021). "The most interesting observation was from patient #4, a histologically diagnosed adenocarcinoma, in which we found that when compared with other epithelial clusters, cluster 5 preferentially expressed NE markers CHGA and SYP, probably representing a population of early NE precursors." (PMID 33328604, 2020). "IHC analyses confirmed the presence of CHGA positive cells in otherwise conventional adenocarcinomas of the colon, and outlined an occult neuroendocrine differentiation in one case (ID-08) with very high levels (10-times higher than those of the lowest detectable case)." (PMID 31537838, 2019). "Biopsies from the anal canal tumor, swollen lymph node, and Paget lesion all showed poorly differentiated adenocarcinoma with neuroendocrine features expressing synaptophysin and chromogranin A. Serum CEA and NSE levels were high, 809.4 ng/ml and 85.8 ng/ml, respectively." (PMID 30458812, 2018). "Positive markers for the adenocarcinoma component included CK8/18, CDX2, and C-erB-2, whereas positive markers for the neuroendocrine component included chromogranin A, synaptophysin, CD56, and a high Ki-67 index (~40%)." (PMID 40909957, 2025). "In our study, an immunohistochemistry panel with specific markers was performed in all MiNEN cases, evidencing the presence of both neuroendocrine components (chromogranin A, synaptophysin, CD56, CK35BH11) and adenocarcinoma cells (AE1/AE2, CDX2, CK7, CK20)." (PMID 34201925, 2021). "Chromogranin A, synaptophysin, CD56, CK35BH11 were used for the neuroendocrine lineage and AE1/AE2, CDX2, CK7, CK20 to confirm the existence of adenocarcinoma cells." (PMID 34201925, 2021). "Pathology review and immunohistochemistry for phenotypic markers (AR, PSA, PSMA, ERG, chromogranin A, synaptophysin, and CD56) showed that 9 research-ready PDXs are adenocarcinoma, 7 are neuroendocrine, and 1 has mixed pathology." (PMID 34413304, 2021). "These include neuroendocrine markers in UWG01CTC such as chromogranin A, CD56, and synaptophysin, and cytokeratin markers seen in adenocarcinomas in UWG02CTC." (PMID 31953491, 2020). "Recently, mixed forms between adenocarcinoma and neuroendocrine prostate cancer (NEPC) have emerged that are characterized by persistent androgen receptor (AR)-signalling and elevated chromogranin A (CgA) levels." (PMID 30337589, 2018). "Immunohistochemically, the adenocarcinoma cells were positive for CEA but negative for chromogranin A (CgA) and synaptophysin (Syn), while the non-adenocarcinoma cells were positive for the expression of CgA and Syn but negative for CEA." (PMID 27848241, 2016). "In addition, epithelial cells of patient #6 consisted of a group of NE cells (cluster 4, expressing ASCL1, CHGA, and CHGB), a group of basal cells (cluster 8, expressing KRT5, KRT14, and KRT15) as well as the remaining ARhigh luminal cells, presenting mixed features of both adenocarcinoma and NEPC." (PMID 33328604, 2020).
adenocarcinoma (continued). "Immunohistochemically, the NEC cells were diffusely positive for synaptophysin, with focal expressions of INSM1, chromogranin A and NCAM, whereas the adenocarcinoma cells were mostly negative for these NE markers." (PMID 35801304, 2022). "Cells of the adenocarcinoma component were CAM.5.2, CK7, CK AE1/AE3, and GATA-3 positive and negative for synaptophysin, chromogranin A, parathormone, parafibromin, thyroglobulin, TTF1, calcitonin, glucagon, S100, PGP-9 and Bcl-2." (PMID 32506375, 2021). "It is characterized by small neuroendocrine (NE)-like cells which typically express NE markers such as chromogranin A (CHGA) and synaptophysin (SYP) and do not express androgen receptor (AR) or adenocarcinoma markers, such as prostate-specific antigen (PSA)." (PMID 25544761, 2015). "All adenocarcinoma were positive for either PSA and/or PSMA on IHC while none expressed chromogranin-A, synaptophysin, or CD56 (N-CAM) except one focally positive for synaptophysin." (PMID 29147414, 2015). "The histological review identified LU2E as an SCLC sample, showing positive staining for chromogranin A, synaptophysin, and CD56, but negative for NapsinA, whereas LU2D was identified as an acinar predominant adenocarcinoma, with negative staining for chromogranin A and synaptophysin." (PMID 37799479, 2023).
infection (15 papers, 2010 to 2025). The state of being infected such as from the introduction of a foreign agent such as serum, vaccine, antigenic substance or organism. "Immunofluorescence-based analyses indicated that HRV primarily infected E-cadherin-positive enterocytes, with infection also identified in chromogranin A-positive enteroendocrine cells, suggesting that HRVs exhibit a cell-type specificity of infection." (PMID 29534451, 2018). "Ad-RFP-Neurog3 infection induced expression of the pan-endocrine markers chromogranin A (CHGA) and synaptophysin in both primary CD133+ duct cells and cultured spheres (and data not shown)." (PMID 24252877, 2013). "We fractionated cells produced by Ad-RFP-Neurog3 infection by RFP intensity and measured mRNA expression of Neurog3, CHGA, SST and GHRL by qRT-PCR." (PMID 24252877, 2013). "Immunostaining confirmed these qRT-PCR findings and demonstrated that only RFP+ cells produced by Ad-RFP-Neurog3 infection were immunostained with antibodies recognizing NEUROD1, NKX2.2, CHGA, SST or GHRL." (PMID 24252877, 2013). "Moreover, the abundance of the panendocrine cell markers chromogranin A (CHGA) and CHGB, which are weakly upregulated during the early stages of infection, was decreased from 17 to 48 DPI, and ChgB was significantly transcriptionally downregulated from 13 to 48 DPI compared to UI mice." (PMID 35100877, 2022).
breast (4 papers, 2013 to 2025). "In our patient, the immunohistochemical studies done for both the ovarian and the gall bladder malignancies showed a positivity for the epithelial membrane analyzer, chromogranin A, and neuron specific enolase hence classifying them into the neuroendocrine group." (PMID 24371533, 2013).
gastrointestinal tumors (2 papers, 2023 to 2024). "Recently, INSM1 has emerged as an additional general neuroendocrine marker because it was shown to have better diagnostic ability than synaptophysin and chromogranin A in gastrointestinal tumors." (PMID 37027114, 2023).
cardiovascular disease (1 paper, 2025). "Paradoxically, this allele was also associated with a lower risk of cardiovascular disease, suggesting pleiotropic effects potentially mediated by its regulatory effects on CHGA expression across different tissues." (PMID 41018225, 2025).
gastrointestinal disease (1 paper, 2020). A disease that occurs in the gastrointestinal system, excluding the hepatobiliary system. "Derivatives of ChgA have been also connected to the pathophysiology of gastrointestinal diseases." (PMID 32110996, 2020).
renal disease (1 paper, 2021). "A polymorphism in the CHGA 3’-untranslated region known as C+87T (rs7610), promotes increased inhibition of CHGA by miR-107, leading to increased sympathetic nerve activity, autonomic dysregulation, increased blood pressure and renal disease in a hypertensive mouse model." (PMID 34944415, 2021).
CHGA also shares sentences with these, for which no sentence is quoted: depression (7 papers); cholelithiasis (3); essential hypertension (3); gastric tumor (3); gastrinoma (3); glomus tumor (3); neurodegenerative disease (3); neurological diseases (3); pancreatic ductal adenocarcinoma (3); thyroid cancer (3); type 1 diabetes (3); adrenal cortical tumors (2); Autoimmunity (2); clear cell carcinoma (2); frontotemporal lobar degeneration (2); gallbladder adenocarcinoma (2); gingivitis (2); large cell neuroendocrine carcinoma (2); leiomyoma (2); liver cancer (2); lymphocytic colitis (2); myocardial infarction (2); pancreatic (2); pancreatic cancer (2); schwannoma (2); Sepsis (2); Takayasu arteritis (2); thyroid tumours (2); adrenal pheochromocytoma (1); AIDS (1).
A further 83 diseases each share a sentence with CHGA in 1 paper.